WT1 (WT1 transcription factor)
Diseases named in the same sentence as WT1 in open-access papers (continued):
Sharing a sentence is not in itself a finding about the gene and the disease.
blood cancers (6 papers, 2016 to 2025). "The Wilms’ tumor protein 1 (WT1) is a well-known and prioritized tumor-associated antigen expressed in numerous solid and blood tumors." (PMID 39259326, 2025). "The transcription factor WT1 is overexpressed in several blood cancers and contributes to several known MHC class I associated epitopes." (PMID 32153583, 2020). "Several immunotherapies have been devised to target TAA derived from proteins, such as WT1, NY-ESO-1, PRAME, Proteinase 3, MAGE-A3 in blood cancers and despite inherent limitations, TAA have practical advantages for the design of immunotherapies." (PMID 32153583, 2020).
gynecologic tumor (4 papers, 2018 to 2024). "These reported data have important differential diagnostic implications since WT1 IHC is generally believed as the most reliable tool in the distinction between ovarian and endometrial origin of gynecological tumors." (PMID 32859123, 2020). "In summary, WT1 overexpression indicates a poor prognosis in patients with some gynecological tumors, but more studies are needed to confirm these findings." (PMID 29995811, 2018).
hematological cancer (4 papers, 2014 to 2025). "WT1-specific T-cells have previously been minutely observed in both healthy controls and patients with hematological cancers." (PMID 40847198, 2025). "To assess WT1-specificity in hematological cancers via TCRGP models, we compiled TCRβ cohorts of healthy donors, AML, MDS, and CML patients and single-cell RNA + TCRαβ cohorts of AML and CML patients, as described in Materials and Methods." (PMID 40847198, 2025). "This is further evidenced by superior activation of both the WT1-specific CD8+ T-cell clone used in this paper and antigen-specific CD8+ T-cells from hematological cancer patients after stimulation with IL-15-transpresenting DC." (PMID 28785596, 2017). "An expression analysis in the 26 of the hematological cancer cell lines and 53 primary AML samples revealed GATA-2 and WT1/AWT1 co-expressed in 96% cases (51/56) consistent with this mechanism being a regulator of expression at the locus." (PMID 24405639, 2014).
cardiac disease (2 papers, 2021). "Wt1 is further implicated in cardiac disease and repair in adult life." (PMID 34299295, 2021). "Here, we review the history of investigations characterizing the role of WT1 (i) in cardiac development, (ii) in cardiac disease and regeneration, and (iii) in different cardiac cell types and transcriptional regulatory mechanisms." (PMID 34299295, 2021).
endocrine tumors (1 paper, 2016). "Further studies of menin and WT1 in specific tissues, especially endocrine tumors, are warranted." (PMID 26871472, 2016).
metabolic disease (1 paper, 2022). A congenital disorder (due to inherited enzyme abnormality) or acquired (due to failure of a metabolically important organ) disorder resulting from an abnormal metabolic process. "Reducing Wt1 expression in this and other intra-abdominal fat depots may represent a novel treatment strategy in metabolic disease." (PMID 34846543, 2022). "Thus, our results identify WT1 as a repressor of brown adipocyte identity and a potential therapeutic target in metabolic disorders." (PMID 34846543, 2022).
neurodevelopmental disorder (1 paper, 2015). A behavioral and cognitive disorder with onset during the developmental period that involves impaired or aberrant development of intellectual, motor, or social functions. "As far as we know, only 14 cases were found to carry genomic microdeletion encompassing PAX6 or its regulatory region but not WT1 to date, and only one of them displayed neurodevelopmental disorders." (PMID 25628759, 2015).
neurological disorders (1 paper, 2009). "These include genital abnormalities (WT1), eye defects (LAMB2), and neurological disorders (Mowat–Galloway)." (PMID 17968594, 2009).
WT1 also shares sentences with these, for which no sentence is quoted: glomerulopathy (13 papers); genetic disease (6); Intellectual disability (6); germ cell tumor (5); peritoneal mesothelioma (5); Renal neoplasm (5); head and neck squamous cell carcinoma (4); leiomyosarcoma (4); myxoid liposarcoma (4); oral cancer (4); rhabdoid tumor (4); Beckwith-Wiedemann syndrome (3); cardiovascular diseases (3); childhood kidney cancer (3); clear cell sarcoma of the kidney (3); endometrial stromal sarcoma (3); endometrial stromal tumor (3); Glomerular sclerosis (3); metanephric adenoma (3); minimal change nephrotic syndrome (3); mucinous carcinomas (3); nephrosis (3); alveolar rhabdomyosarcoma (2); B-cell acute lymphoblastic leukemia (2); benign prostatic hyperplasia (2); brain cancer (2); cerebral gigantism (2); cervical adenocarcinoma (2); childhood tumor of the kidney (2); combined immunodeficiency (2).
A further 167 diseases each share a sentence with WT1 in 2 papers or fewer.